HLA-G (major histocompatibility complex, class I, G)
Diseases named in the same sentence as HLA-G in open-access papers (continued):
Sharing a sentence is not in itself a finding about the gene and the disease.
viral infections (continued). "HLA-E surface levels serve as an important sensor of HLA class I expression and are sensitive to perturbations in the biosynthesis of most polymorphic class I allotypes as well as the class Ib molecule HLA-G imparted by viral infections or stress." (PMID 32132995, 2020). "Since HLA-G was similarly induced by virus infection and U94 gene/protein treatment, we focused on transcriptional factors that were similarly modulated in all experimental conditions." (PMID 30523283, 2018). "HLA-G expression is involved in tumor escape from immunesurveillance, tolerogenic responses in transplantation, and importantly, blood HLA-G expression increases in viral infections." (PMID 28769934, 2017). "Many reports highlighted the importance of HLA-G either in viral infections or in solid allograft acceptance after transplantation, though only a minority focused on the role of HLA-G for CMV infection in an allogeneic setting after transplantation." (PMID 29113092, 2017). "In the last years, the role of HLA-G in the progression of different infectious diseases has been fully described, for both microbial and viral infections." (PMID 27652273, 2016). "HLA-G expression increases strongly during viral infections such as congenital human cytomegalovirus (HCMV) infections, with functional consequences in immunoregulation." (PMID 27699182, 2016). "Neo-ectopic or aberrant expression of HLA-G has frequently been related to malignancies, viral infections including liver-related hepatitis B and C virus infections, autoimmune disorders, inflammatory diseases, complications, and transplantation outcomes." (PMID 27199995, 2016). "Interesting, during viral infections, HLA-G molecules are up-regulated by the virus as a mechanism of immune-escape inhibiting the host immune response." (PMID 27443345, 2016). "The main challenge would be to block HLA-G up-regulation by viral infection, in order to allow the recognition by immune cells." (PMID 25477881, 2014). "Nevertheless, HLA-G is up-regulated in different pathological conditions, such as transplantation, tumors, viral infections, and inflammatory diseases." (PMID 25202308, 2014). "Human leukocyte antigen-G (HLA-G) was first detected on cytotrophoblast cells at the feto-maternal interface but its expression is prevalent during viral infections and several autoimmune diseases." (PMID 25477881, 2014). "HLA-G and HLA-E can co-operate to establish an immunosuppressive microenvironment in human tumors and viral infections, facilitating the escape of transformed cells from the recognition by the immune system." (PMID 25202308, 2014). "This review aims to focus on the key role of HLA-G molecules in autoimmune diseases and viral infections." (PMID 25477881, 2014). "The peripheral cells expressing HLA-G during viral infections are monocytes and T lymphocytes (HIV, influenza)." (PMID 24839609, 2014). "Recently, some studies reported that the HLA-G molecules have a complex immune regulatory role, these molecules may be either compensatory or pathogenetic in different process like viral infections and chronic inflammatory diseases like asthma." (PMID 40573358, 2025). "HLA-G is an HLA-class Ib molecule and is known to be overexpressed in the placenta for fetal-maternal tolerance, in cancer tissues, and in inflammatory and viral diseases." (PMID 38022530, 2023). "Several haplotypes have been described in the 3’UTR (UTR-1, UTR-2, UTR-3, UTR-4, UTR-5, UTR-6/-18, and UTR-7) of this gene, suggesting that HLA-G may influence immune responses to different stimuli, including in viral infections." (PMID 37342325, 2023). "Thus, the regulation of HLA-G expression upon viral infection is complex and further studies are urgently needed to gain deeper insights into the molecular mechanisms of the viral infection-driven HLA-G neoexpression." (PMID 35237271, 2022).
viral infections (continued). "Indeed, IL-10 is a known inducer of the HLA-G expression and has also been described in tumor cells independently of viral infections as inducer of HLA-G expression." (PMID 35237271, 2022). "Soluble form of HLA-G (sHLA-G) has been measured in the serum or plasma, secreted by monocytes or T cells in pathological conditions, such as inflammatory diseases or viral infections, or in neoplastic and autoimmune disorders, but also in response to solid organ transplantation." (PMID 35355984, 2022). "The non-classical histocompatibility antigen G (HLA-G) is an immune checkpoint molecule that has been implicated in viral disorders." (PMID 36077133, 2022). "However, HLA-G expression can be induced in cancers, transplantation, multiple sclerosis, inflammatory diseases, and viral infections." (PMID 34659215, 2021). "HLA‐G has been intensively investigated in viral infectious diseases." (PMID 32399213, 2020). "In this scenario, human leucocyte antigen‐G (HLA‐G) and its immune cell surface‐expressed receptor signalling pathway has been well known to modulate the functions of T cells, B cells and NK cells, and is involved in viral infection." (PMID 32399213, 2020). "Furthermore, the results indicate for the first time that virus infection induces ATF3, which is able to interact directly with the HLA-G promoter, finally inducing the HLA-G production associated to virus infection." (PMID 30523283, 2018). "We believe that by including a screening step for selecting only HLA-G polymorphic sites that contribute to susceptibility to viral infection, we minimize the inclusion of genetic factors not related to it." (PMID 30278059, 2018). "Differential splicing and translation of HLA-G may also alter viral disease progression by various mechanisms." (PMID 28769934, 2017). "Myeloid APCs were shown to express HLA-G in pathological context (e.g., in cancer and viral infections); it was suggested that HLA-G-expressing myeloid APCs may be viewed as suppressor cells." (PMID 27529074, 2016). "Since both MS disease and viral infection are characterized by an increase in HLA-G expression we could hypothesize a synergic effect of these two conditions in the maintenance of a dysregulated immune response in MS patients." (PMID 27443345, 2016). "An upregulation of HLA-G expression has been reported in most studies of viral infection." (PMID 24839609, 2014). "Protease levels generally increase during bacterial and viral infections and this may lead to the proteolytic shedding of membrane-bound HLA-G in a soluble form, resulting in an increase in blood HLA-G concentration." (PMID 24839609, 2014). "However, HLA-G can be ectopically expressed also on monocytes, in transplantation, tumors, viral infections, and autoimmune diseases." (PMID 25477881, 2014). "The increase in the secretion of cytokines, including interferons in particular, during the course of viral infection, and the use of interferons as therapeutic agents may account for the increase in HLA-G levels." (PMID 24839609, 2014). "As far as viral infections are concerned, HLA-G could be considered a target for anti-viral treatment, so increased knowledge in this field could contribute to identifying different therapeutic strategies." (PMID 25477881, 2014). "Alternatively, HLA-G expression or secretion may reflect an appropriate and efficient response to the inflammatory process occurring during viral infection or septic shock." (PMID 24839609, 2014). "In fact, it appears even more evident that HLA-G proteins are involved in the regulation of the immune system during autoimmunity, such as gastrointestinal, skin, rheumatic and neurological diseases and in the immune-escape mechanisms during viral infections." (PMID 25477881, 2014). "The HLA-G, a non-classical HLA class I molecule, has been shown to play a critical role in immune response modulation and has been implicated in various pathological processes including response to viral infections." (PMID 37342325, 2023).
viral infections (continued). "HLA-E and HLA-G are immunoregulatory molecules and their cooperation has been found in immunosuppressive environments, including physiological (immune tolerance at maternal/fetal interface during pregnancy) and pathological (immune evasion of both tumor and viral infection) conditions." (PMID 37529053, 2023). "Thus, targeting of HLA-G, its receptors, or HLA-G-relevant molecules might offer a novel therapeutic strategy for malignant tumors and also viral infections." (PMID 36334153, 2022). "Finally, a clinical phase I trial with an HLA-G blockade antibody, TTX-80, was launched in July 2020 for patients with advanced solid cancer, which shed new light on the restoration of exhausted immune responses induced by HLA-G in diseases such as cancers or viral infections." (PMID 34938296, 2021). "However, HLA-G can be expressed de novo at high levels in several pathological conditions, including solid and hematological tumors and during microbial or viral infections, leading to the impairment of the immune response against tumor cells or pathogens, respectively." (PMID 27652273, 2016). "HLA-G and HLA-E interaction may also take place during viral infections." (PMID 25202308, 2014). "The knowledge of the interactions between HLA-G molecules and immune mechanisms and their implication in pathological conditions may assist in improving our knowledge on the mechanisms at the basis of several autoimmune diseases and viral infections." (PMID 25477881, 2014). "HLA-G antigens are currently considered as immune-modulatory molecules due to their role in preserving immune tolerance at the feto-maternal interface, promoting graft tolerance, reducing inflammatory and immune responses, favoring tumors, and virus infection via immune escape." (PMID 25477881, 2014). "However, the role of HLA-G in viral infections remains unclear, because two hypotheses are possible." (PMID 24839609, 2014). "The restricted expression of HLA-G and the fact that HLA-G on the one hand is important for successful embryo implantation and fetal survival but, on the other hand, being potentially detrimental in tumors and viral infections suggest that the expression of HLA-G is tightly regulated." (PMID 22438923, 2012). "Two hypotheses have been proposed to explain this discrepancy: the first is that the immunosuppressive action of HLA-G enhances the virus’s ability to escape the immune system, while the second is that HLA-G expression and secretion are a robust response to inflammation during the viral infection." (PMID 37342325, 2023). "While the role of HLA‐G in organ transplantation, pregnancy and cancer is well documented, its involvement in viral infections has not yet been sufficiently studied." (PMID 40910405, 2025). "In this regard, a growing body of evidence indicates that the nonclassical human leukocyte antigen-G (HLA-G), which is highly expressed in trophoblast cells and viral infections, has a crucial immune modulatory role." (PMID 35877415, 2022). "This characteristic gives HLA-G a beneficial modulatory effect on pregnancy, autoimmune and inflammatory diseases, and negative effects on cancer and viral infections." (PMID 36077133, 2022). "HLA-G is a non-classical HLA class I antigen, which is pondered as an immune inhibitory mediator and can be up-regulated by several viral infections, including SARS-CoV-2, which can render comprehensive immunosuppressive roles in favoring virus immune evasion and subsequent disease progression." (PMID 35625532, 2022). "In SSc studies, it was found that the serum HLA‐G (sHLA‐G) levels in SSc patients with human herpesvirus‐6 (HHV‐6) infection were significantly increased and that the production of sHLA‐G in endothelial cells can possibly inhibit angiogenesis in the presence of a viral infection." (PMID 33657268, 2021). "Thus, HLA-G expression and/or secretion might reflect a negative feedback response to inflammatory processes during viral infections." (PMID 36334153, 2022).
ovarian carcinoma (43 papers, 2008 to 2024). A malignant neoplasm originating from the surface ovarian epithelium. "In contrast, higher HLA-G levels in the bladder UC, renal clear cell carcinoma, renal cell carcinoma, hepatocellular carcinoma, lung adenocarcinoma, and ovarian carcinoma groups were significantly associated with longer DFS." (PMID 39594832, 2024). "HLA-G and HLA-E in ovarian cancer are potentially associated with the mechanism of disease progression." (PMID 34868310, 2021). "Five studies investigated the association between HLA-G expression and clinical outcome of ovarian carcinoma patients." (PMID 34361031, 2021). "As ILT4, HLA-G was associated with tumor metastases and poor survival in an animal model of ovarian cancer." (PMID 32620162, 2020). "Downregulation of classical HLA is associated with an unfavourable prognosis in ovarian cancer; however, the association of HLA-G with prognosis is controversial." (PMID 24987709, 2014). "HLA-G expression is associated with tumor metastasis and poor survival in the Balb/c nu/nu mouse model of ovarian cancer." (PMID 24839609, 2014). "Moreover, increased amount of HLA-G-bearing extracellular vesicles (HLA-GEV) predisposed epithelial ovarian cancer patients to disease progression and poor prognosis, being indicative of higher disease risks." (PMID 38310272, 2024). "Furthermore, HLA-G expression is associated with metastasis and poorer survival in a humanized murine model of ovarian cancer, playing a key role in fostering immune tolerance and constitutes an escape mechanism of tumor cells." (PMID 38162657, 2023). "HLA-G expression is also linked with poorer prognosis in breast and ovarian cancers." (PMID 33671917, 2021). "Moreover, the vesicular‐bound HLA‐G was associated with a high risk of ovarian cancer progression." (PMID 35759240, 2022). "HLA-G was aberrantly enriched in a variety of tumors, including colorectal cancer, gastric cancer, ovarian cancer, thyroid cancer, cervical cancer, and endometrial cancer." (PMID 38310272, 2024). "Several in vitro studies have demonstrated that NK cells can more effectively eliminate HLA-G-negative leukemia, glioma, ovarian carcinoma, and hepatocellular carcinoma cell lines than those transfected with HLA-G." (PMID 38542078, 2024). "For example, one of the mechanisms of ovarian cancer evading immune surveillance is to upregulate human leukocyte antigen-G (HLA-G) expression." (PMID 36765541, 2023). "In preclinical immunocompetent models, the HLA-G expression in human ovarian carcinoma cell lines has demonstrated an increased capacity for migration and invasion compared to their HLA-G negative counterpart in nude mouse models." (PMID 38162657, 2023). "We then found that HLA molecules are overexpressed in high-risk groups, consistent with other studies on HLA molecules in ovarian cancer; HLA-G is a potential biomarker of advanced and complex ovarian cancer." (PMID 34868310, 2021). "HLA-G expression was demonstrated to be frequent in ovarian cancer (55%) with progression during disease development." (PMID 32922387, 2020). "Similar findings were reported in a study with epithelial ovarian cancer (EOC) patients in which high levels of HLA-G EVs was a marker of inferior clinical outcome." (PMID 32922387, 2020). "HLA-G gene in ovarian cancer had an HR = 0.81 (95% CI, 0.71–0.93) and logrank p-value = 0.0023; therefore the result was statistically significant (the relation between the high expression of HLA-G gene and more survival rate)." (PMID 32867672, 2020). "HLA-Gs are a valid target in cancer therapy; cytotoxicity studies show that HLA-Gs drastically inhibit lysis of human ovarian carcinoma cells, with subsequent immune evasion, and that lysis can be restored by the conformational anti-HLA-G mAb 87G." (PMID 30899759, 2019). "Concerning ovarian cancer, so far only one study placed emphasis on the analysis of the HLA-G expression in primary tumor lesions and metastatic tissue." (PMID 30932005, 2019).
ovarian carcinoma (continued). "In this context, we presented similar puzzled data of staining pattern (mAbs 4H84neg5A6G7pos) on the case-matched lung and ovarian cancers and lead to hot discussion by the participants during the 7th international conference on HLA-G (Paris, 2015." (PMID 30234020, 2018). "Cho as well as Sheu and Shih found that high expression of HLA-G/sHLA-G and a high level of IL-10 in the micro-environment of ovarian cancer contribute to an aggressive course of the disease." (PMID 28376925, 2017). "The same authors found expression of HLA-G on ovarian cancer cells and documented its role in immune escape of this malignancy." (PMID 28376925, 2017). "In conclusion, expression of HLA-G is an independent prognostic factor for improved survival in high grade epithelial ovarian cancer and a predictor for platinum sensitivity." (PMID 24987709, 2014). "Improved survival of patients with epithelial ovarian cancer expressing HLA-G in tumour cells in ascites has been described." (PMID 24987709, 2014). "The same controversies regarding prognosis are seen between studies analysing HLA-G expression in ovarian cancer." (PMID 24987709, 2014). "In agreement with our results, it has been recently reported that the 4 CpG sites in the HLA-G promoter region contained a hypoxia response element (HRE) that remained completely methylated in ovarian cancer cell lines." (PMID 20419139, 2010). "This was also seen in ovarian cancer where HLA-G was not only expressed in high-grade serous carcinoma but also conferred tumour cells aggressiveness." (PMID 19755991, 2009). "Differences in methylation within the 5' regulatory region of HLA-G were detected between normal ovarian surface epithelial cells and ovarian cancers." (PMID 18498645, 2008). "In ovarian cancer, compared to the tumor cells in situ, metastatic tumor cells in ascites had higher expression of HLA-G, which was inversely correlated to the frequency of immune cell infiltration and positively related to disease progression, tumor metastasis, and poor prognosis." (PMID 38310272, 2024). "This immune evasion mechanism has also been functionally proven in ovarian cancer, where HLA-G directly inhibited NK cell mediated cancer cell lysis, which could be disinhibited by blocking of HLA-G." (PMID 39469714, 2024). "HLA‐G is significantly expressed in ovarian cancer and may directly inhibit the lysis of NK‐92 cells in in vitro experiments." (PMID 35759240, 2022). "In ovarian cancer, HLA-G expression correlated with an elevated expression of tumor marker CA-125 and a combination of both serum markers could improve the clinical screening and diagnosis." (PMID 35185904, 2022). "Further functional study indicated that HLA-G could inhibit NK cell cytotoxicity and thus assist ovarian carcinomas to escape from human immune surveillance." (PMID 33868274, 2021). "Our in vivo study provided that blocking HLA-G with a specific neutralizing antibody can inhibit the growth of HLA-G-positive tumor cells and restore antitumour immunity against HLA-G-positive tumor cells in a humanized mouse model of ovarian cancer." (PMID 34276642, 2021). "Positive HLA-G expression was highly represented in patients with ovarian carcinoma recurrence." (PMID 34276691, 2021). "Interestingly, following 5-aza-dC treatment of ovarian cancer cells (BG-1) HLA-G −242 site was shown to remain methylated, while hypomethylation of sequences was observed within 5′ HLA-G regulatory region." (PMID 27577073, 2016). "In conclusion, this is the first study to describe the correlation of classical and nonclassical HLA class I expression levels with survival in high grade epithelial ovarian cancer and to correlate both membrane-bound and soluble HLA-G protein and HLA-G gene expression." (PMID 24987709, 2014).